IL6 (interleukin 6)
Diseases named in the same sentence as IL6 in open-access papers (continued):
Sharing a sentence is not in itself a finding about the gene and the disease.
prostate carcinoma (continued). "Biological evidences that correlate inflammation with prostate cancer initiation, progression and prognosis are based on different cytokines like IL-6, IL-8, MIC-1." (PMID 28389628, 2017). "Together, these findings indicate that IL-6 contributes to prostate cancer progression through multiple activities." (PMID 28292326, 2017). "In prostate cancer, inhibition of IL-6 secretion increases the sensitivity of prostate cancer cells to anticancer drugs." (PMID 29296206, 2017). "Playing critical roles in immune responses, interleukin-6 (IL-6) has been proposed to be involved in the development of multiple cancers, including prostate cancer." (PMID 28296724, 2017). "Based on the present results, we have updated our previously-reported melatonin MT1 receptor antiproliferative pathway in prostate cancer with bi-directional positive interactions between AR-V7 and NF-κB/IL-6 signaling." (PMID 28561752, 2017). "A great deal of clinical and experimental evidence suggests that IL-6 promotes prostate cancer progression." (PMID 28292326, 2017). "Several reports from in vitro studies showed that IL-6 up-regulated prostate-specific antigen mRNA and promoted androgen-independent growth in human prostate cancer cells." (PMID 28783760, 2017). "Dietary induced weight loss in non-oncological populations has shown reductions in inflammatory cytokines (IL-6 and IL-8) associated with CRF, suggesting weight loss in obese men with prostate cancer to be a plausible and measurable nutrition therapy outcome." (PMID 28895922, 2017). "Anti-IL-6 monoclonal antibody suppressed the progression from androgen-dependent prostate cancer to an androgen-independent prostate cancer in orchiectomized mice." (PMID 28783760, 2017). "Since IL-6 signaling pathway includes STAT3, we performed Western blot studies to assess the status of p-STAT3 in the different prostate cancer cell lines following IL-6 treatments." (PMID 28467474, 2017). "Among these tumor-derived cytokines, IL-6 has been proposed to be an efficient MDSCs inducer in solid tumors, such as esophageal cancer, prostate cancer, and melanoma." (PMID 29326716, 2017). "This study focuses on the regulation of PCAT29, a tumor suppressor lncRNA by IL-6 in prostate cancer cells." (PMID 28467474, 2017). "Previously, inflammatory cytokines such as IL-6 and IL-8 have been reported to stimulate the growth of prostate cancer cells, especially androgen-independent prostate cancer cells." (PMID 27626693, 2016). "Collectively these data support a role of IL-6 in expanding the prostate cancer stem-like phenotype and suggest that ESE3/EHF controls both basal and IL-6 induced STAT3 response." (PMID 27732936, 2016). "Using a prostate cancer cell line, dihydrotestosterone confirmed that it requires the androgen receptor to inhibit IL-6 gene promoter." (PMID 28066415, 2016). "Given the role of IL-6 in the activation of androgen receptors, neuroendocrine differentiation and angiogenesis in prostate cancer development, attempts have been made to inhibit the cytokine signalling pathways using monoclonal antibodies." (PMID 27538520, 2016). "Cytokine IL-6 stimulates prostate cancer growth by stimulating the androgen receptor, and is involved in the development of bone metastasis." (PMID 27129164, 2016). "Other authors confirmed that irradiation enhanced IL-6 expression and showed that the increased growth and angiogenesis of murine hormone resistant versus hormone sensitive prostate cancer cells was attributable to higher IL-6 production." (PMID 27500125, 2016). "On the other hand, in a study of the pathophysiology of cachexia in patients with prostate cancer, a serum cytokinome profile of 10 biomarkers (IL-1β, IL-2, IL-4, IL-5, IL-6, IL-8, IL-10, IL-12, IFN-γ, and TNF-α) was evaluated." (PMID 28050120, 2016).
prostate carcinoma (continued). "Some cytokines, including IL-3, IL-6, and IL-16, ended up being upregulated in prostate cancer patients and others, including Fas/TNFRSF6, TRALR-3, and IGFBP-6, markedly downregulated." (PMID 28050120, 2016). "MAPK signaling and IL-6-induced neuroendocrine differentiation was increased in LNCaP prostate cancer cells, similar to activities observed in patients undergoing ADT." (PMID 26828526, 2016). "Several phase I/II clinical trials are currently evaluating antibodies against IL-6 or IL-6R as therapeutic alternatives for prostate cancer and renal cancer." (PMID 26989335, 2016). "Chronic inflammation is one of the most important factors in prostate cancer etiology and carcinogenesis, and plasma IL-6 level has prognostic significance in patients with hormone-refractory prostate cancer." (PMID 27129164, 2016). "In prostate cancer, the levels of serum IL-6 range from 1.5–2.2 pg/mL in localized and locally invaded tumors, which is well below the serum levels reported (~100 pg/mL) when metastatic disease ensues." (PMID 27351281, 2016). "For example, IL-6 is an autocrine and paracrine growth factor for prostate cancer cell lines and functions as a resistance factor for cisplatin-mediated cytotoxicity." (PMID 27129164, 2016). "Based on this observation IL-6/STAT3 signaling inactivation was proposed as possible treatment for prostate cancer." (PMID 28005952, 2016). "For instance, leptin and interleukin-6 showed in vitro to have a supporting activity in prostate cancer cell lines inducing proliferation, inhibiting apoptosis and increasing migration." (PMID 26846521, 2016). "It is often reported that TAMs in the tumor microenvironment along with their secreted cytokines, such as IL-6, interact with prostate cancer cells and play an important role in neuroendocrine differentiation and the prognosis of prostate cancer." (PMID 27034164, 2016). "While the role of IL-6 in prostate cancer is well documented, studies on serum IL-18 for its diagnostic utility in cancer are limited." (PMID 27429614, 2016). "The PI3K–protein kinase B (PkB)/Akt pathway also plays an indispensable role in the transduction of IL-6 signal, especially in the antiapoptotic effect of IL-6 in prostate cancer cells." (PMID 28066415, 2016). "Overexpression of STAT3 and its main regulator IL6 is reported in the literature but IL6 inhibitory effect in prostate cancer progression and failure of STAT3-IL6 axis targeting as potential therapeutic target in patients were reported as well." (PMID 28005952, 2016). "Inflammatory cytokines such as IL-6 and IL-8 have been reported to stimulate the growth of prostate cancer cells especially androgen-independent prostate cancer cells." (PMID 27626693, 2016). "We have previously reported that IL-6 is induced in prostate cancer cells and that the ETS factor ESE1 was an important mediator enhancing the NFKb response." (PMID 27732936, 2016). "Knockdown of GPR160 in prostate cancer cells increased the expression of caspase 1 and IL-6, induced cell cycle arrest and apoptosis, though the underlying molecular mechanism remains to be identified." (PMID 26871479, 2016). "IL-6 is a major activator of the Janus kinase/signal transducer and activator of transcription 3 pathway in prostate cancer." (PMID 26252635, 2015). "It was reported that down-regulation oflet-7 in cancer-associated mesenchymal stem cells (MSCs) results in the enhanced secretion of IL-6, and IL-6 then promotes prostate cancer cell metastasis." (PMID 26123544, 2015). "Interleukin-6 (IL-6) is a pleiotropic cytokine that stimulates proliferation and modulates key cellular events in prostate cancer." (PMID 26252635, 2015). "In the first study, Abdul and Hoosein (2001) showed that carbamazepine and phenytoin both reduced secretion of prostate-specific antigen (PSA) and interleukin-6 (IL-6) in prostate cancer cells." (PMID 26834632, 2015).
prostate carcinoma (continued). "This study provides experimental data to drive future efforts in prostate cancer gene therapy and diagnosis that are based on IL-6, miR-21, and PDCD4." (PMID 26252635, 2015). "IL-6-mediated activation of STAT3 in human prostate cancers is well documented and related to androgen-independence." (PMID 26046794, 2015). "In the present study, the prostate cancer cells and co-cultures also expressed high levels of IL-6, IL-8 and Gro-α; however, only CCL2 levels increased significantly in the co-cultures with monocytes." (PMID 26317041, 2015). "The expression of IL-6 is elevated in advanced prostate cancer and correlates with the Gleason grade of prostate cancer and prostate cancer progression." (PMID 26252635, 2015). "Abdulet al.62 studied the effect of four anticonvulsants (PHEN, carbamazepine, valproate and ethosuxinide) on the secretion of prostate specific antigen and interleukin-6 in different human prostate cancer cell lines." (PMID 27408684, 2015). "IL-6 promotes the proliferation of prostate cancer cells by activating the androgen receptor (AR), and this effect is inhibited by antiandrogens such as bicalutamide." (PMID 26252635, 2015). "The results are in line with our present study showing that IL-6 and IL-11 stimulated the stemness of prostate cancer cells in vitro." (PMID 26528857, 2015). "The cytokine IL-6 activates several prostate cancer pathways, but its upstream trans-signaling pathway remains poorly understood." (PMID 26252635, 2015). "It has been reported that the early growth response 3(EGR3) directly activates the excessive production of IL-6 in prostate cancer and promoted the progression." (PMID 26528857, 2015). "The Gro-α and IL-6 levels were lower in the co-culture supernatants compared with the prostate cancer cells alone." (PMID 26317041, 2015). "In this study, we evaluated the molecular mechanisms of celastrol on cell proliferation and IL-6 gene expression in prostate carcinoma cells." (PMID 24664372, 2014). "Due to the important role of IL-6 in prostate cancer progression, we determined the effect of atorvastatin and/or celecoxib on this cytokine." (PMID 24296978, 2014). "Collectively, in prostate cancer patients an immediate elevation of IL-1β and IL-6 in plasma following irradiation has also been demonstrated." (PMID 24914105, 2014). "Regarding prostate cancer, IL-6 expression is detectable in both epithelium and stroma of human prostates, with increased IL-6 expression in epithelium as the prostate tissues are getting transformation toward malignancy." (PMID 24664372, 2014). "Inflammatory cytokines such as IL-6, IL-8 and TNFα have major role in tumor biology and with this notion in mind; production of these cytokines by prostate cancer cell lines was studied at basal level and after stimulation with LPS and LTA." (PMID 24966802, 2014). "We found for the first time that celastrol inhibited IL-6 secretion and expression in PC-3 cells, one kind of prostate cancer cells, which partly contributed to the anti-proliferative effect of celastrol on PC-3 cell." (PMID 24664372, 2014). "The NE-induced up-regulation of VEGF, IL-8, and IL-6 protein levels was found in a number of human cancer cell lines such as colon cancer, nasopharyngeal cancer, ovarian cancer, prostate cancer and melanoma." (PMID 24555849, 2014). "Further, celastrol represses IL-6 gene expression and secretion in prostate carcinoma cells via the NF-κB signaling pathway." (PMID 24664372, 2014). "It was shown that increased IL-6 expression, which is often seen in advanced prostate cancer, resulted in activation of MMP-9 expression through the TGF-β pathway." (PMID 24978435, 2014). "Interleukin-6 (IL-6), a multifunctional cytokine, contributes to proliferation or differentiation of prostate carcinoma cells in a highly cell type-specific manner." (PMID 24664372, 2014).
prostate carcinoma (continued). "Further investigation into the mitogenic signaling downstream effector of Axl/Akt activation in prostate cancer uncovers NFκB, which also induces the secretion of IL-6 to activate IL-6/STAT3 signaling." (PMID 25344858, 2014). "Previous studies have demonstrated that STAT3 signalling has a critical role in the tumour formation of prostate cancer and IL-6 treatment results in the activation of STAT3 in prostate cancer cells." (PMID 25112532, 2014). "IL-6 is known to be a principal mediator of inflammation frequently elevated in patients with prostate carcinoma." (PMID 24961479, 2014). "For solid tumors, the role of JAK inhibition was examined in models of IL-6-driven breast, ovarian, and prostate cancers using the JAK1/2 inhibitor AZD1480, which led to the suppression of tumor growth." (PMID 24675568, 2014). "The growth inhibition of celastrol against prostate carcinoma cells depends on IL-6 pathway since knockdown of IL-6 blunts the growth inhibition induced by celastrol." (PMID 24664372, 2014). "In a recent study, prostate cancer LNCaP-S17 cells were found to be resistant to exogenous IL-6-induced neuroendocrine differentiation and hence were less aggressive due to increased levels of CIS and SOCS7 that block activation of JAK2-STAT3 pathways." (PMID 24757565, 2014). "Survivin is a downstream target of the signal transducer and activator of transcription 3 (Stat3) that can be activated by IL-6 in prostate cancer." (PMID 24296978, 2014). "Collectively, we concluded that celastrol repressed IL-6 gene expression and secretion and inhibited prostate carcinoma cell growth IL-6-dependently." (PMID 24664372, 2014). "Originally identified as an inducer of the terminal differentiation of B-cells into antibody-producing cells interleukin-6 (IL6) appears to be a major regulator of prostate cancer progression." (PMID 25276782, 2014). "It has been shown that IL-6 is a growth factor for most prostate cancer cells and anti-IL-6 monoclonal antibody has been proven to effectively inhibit xenografted prostate cancer cells growth." (PMID 24664372, 2014). "Interaction between angiogenic endothelial cells and prostate cancer cells has also been reported to activate an IL-6/androgen receptor/TGFβ/gelatinase B/MMP-9 signal pathway that augments prostate cancer invasion in association with angiogenesis." (PMID 24473089, 2014). "Knockdown of ANXA2 inhibits interleukin (IL)-6 secretion in a prostate cancer model under starvation stimulation conditions." (PMID 24591759, 2014). "Serum levels of IL-6 were elevated in prostate cancer patients with more advanced stage disease and correlated with decreased disease-specific survival." (PMID 23864954, 2013). "HR prostate cancer cells had a higher expression of IL-6 and more activated STAT3, compared to TRAMP-C1 cells." (PMID 23806095, 2013). "Our data also showed that overexpressed IL-6 had significant impact on androgen- independent growth and aggressive behavior of prostate cancer." (PMID 23806095, 2013). "The primary outcome of the study is a change in prostate cancer relevant cytokines and hormones (IL-6, MIF, IGF-1, Testosterone)." (PMID 23731674, 2013). "We further examined the effect of irradiation on IL-6/STAT3 signaling in prostate cancer in the present study." (PMID 23806095, 2013). "In prostate cancer, although the critical role of IL-6 in carcinogenesis has been highlighted, its role in the radiation response of prostate cancer requires further investigation." (PMID 23806095, 2013). "The role of IL-6 in the radiation response of prostate cancer was investigated in the present study." (PMID 23806095, 2013). "The precise mechanisms that promote prostate cancer metastasis by environmental IL-6 are not fully understood." (PMID 23977098, 2013).
prostate carcinoma (continued). "Experimental data have proposed IL-6 as a growth factor that regulates the proliferation and survival of prostate cancer cells." (PMID 23977098, 2013). "In studies of acute exercise in healthy individuals, and also in prostate cancer patients undergoing androgen deprivation, serum levels of IL-6, GH and IGF-1 increase." (PMID 23861774, 2013). "Previous studies have shown the ability of NF-kB to promote cell growth and proliferation of prostate cancer cells via various mechanisms, including regulation of c-myc, cyclin D1, Bcl-2 and IL-6." (PMID 24062781, 2013). "Treatment of benign cells with the cytokine led to increased proliferation and an epithelial-mesenchymal transition (EMT) phenotype, which suggests a role for IL6 in the earlier stages of prostate cancer." (PMID 23342084, 2013). "In androgen-independent prostate cancer cells, IL-6 acts as an autocrine and paracrine growth factor, with depletion of IL-6 rendering cancer cells sensitive to chemotherapeutic agents." (PMID 24062781, 2013). "In the present study, we examined the role of IL-6 in the response to radiation and tumor regrowth following radiation in prostate cancer." (PMID 23806095, 2013). "It was reported that IL-6 contributed to the conversion of prostate cancer to an androgen-independent state in xenografts models, and anti-IL-6 monoclonal antibody have been applied to treat metastatic castration-resistant prostate cancer in clinical studies." (PMID 23806095, 2013). "In genito-urinary malignancies, interleukin-6 functions as an autocrine growth factor for renal cell and prostate cancer." (PMID 23497335, 2013). "In future, we will further determine if targeting IL-6 is a useful strategy for sensitizing prostate cancer to irradiation." (PMID 23806095, 2013). "We reported previously that MDSC contributes to tumor promotion in IL-6–positive prostate cancer, at least in part." (PMID 23806095, 2013). "Vashchenko and Abrahamsson reported several new useful treatment agents for NE differentiation in prostate cancer, including somatostatin analogs, serotonin antagonists, bombesin antagonists and inflammatory cytokines, such as interleukin-6." (PMID 23426029, 2013). "Interleukin-6 (IL-6) is a cytokine that regulates growth, differentiation and apoptosis of various types of malignant tumors, including prostate carcinomas by activating the STAT and/or mitogen activated protein kinase (MAPK) signaling pathways." (PMID 24282788, 2013). "IL-6 levels have been shown to be frequently elevated in prostate cancer patients, which is correlated with a poor prognosis and bone metastasis of this disease." (PMID 23977098, 2013). "It was later found to act as an autocrine growth factor in prostate cancer cells, and IL6 protein concentration was found to be up-regulated 18 fold in prostate cancer tissue compared to normal prostate tissue." (PMID 23342084, 2013). "For example, prostate cancer cells express high levels of IL-6, EGF, and EGFR, leading to constitutive activation of JAK2 or Src, which in turn results in STAT3 activation through autocrine and paracrine mechanisms." (PMID 24260381, 2013). "Phenytoin inhibits prostate-specific antigen (PSA) and interleukin-6 (IL-6) secretion, and migration in prostate cancer cells." (PMID 22678159, 2012). "In fact, the mitogenic and anti-apoptoptic effects of several adipokines, alone and combined, in prostate cancer cell growth (e.g. leptin, IL-6, insulin-like growth factor 1, IGF-1), seems to be limited to hormone-refractory prostate cancer cells." (PMID 22469146, 2012).